POSTN (periostin)
Diseases named in the same sentence as POSTN in open-access papers (continued):
Sharing a sentence is not in itself a finding about the gene and the disease.
tumor (continued). "The authors showed that high POSTN expression is strongly associated with poor tumor resectability, even more so than a multi-gene model chosen by LOOCV across 1061 samples in eight datasets including the TCGA and Tothill datasets." (PMID 27287041, 2016). "Stromal periostin protein is associated with versican collagen, and tumor cell epithelial periostin is associated with both versican and vimentin." (PMID 25852822, 2015). "Both the intermediate filament protein nestin and the tumor cell-associated N-glycoprotein periostin were expressed in the cytosol." (PMID 26421614, 2015). "Periostin has been implicated in cardiac development and pathophysiology, tumor survival and invasion, and the fibroproliferative disorder Dupuytren’s contracture." (PMID 26205789, 2015). "This is presumably due to Periostin’s ability to regulate tumour cell invasion and metastasis, as tumour metastasis is associated with the highest rate of mortality for cancer patients." (PMID 26543579, 2015). "We investigated the well-recognized EMT marker N-glycoprotein periostin, both tumor-cell associated and stromal and found it to be associated with sarcomatoid MPM." (PMID 26421614, 2015). "This was further demonstrated by observing a rescue in metastatic efficiency by injecting POSTN-deficient tumor cells into wild-type recipient mice." (PMID 26086719, 2015). "Their results revealed that increased periostin expression in carcinoma cells was significantly associated with high Gleason score and advanced tumor stage." (PMID 21714934, 2011). "Increased periostin expression in carcinoma cells was significantly associated with high Gleason score (p < 0.01) and advanced tumour stage (p < 0.05) in the test cohort." (PMID 20534149, 2010). "Although cancer-associated POSTN overexpression is well documented for some tumor types, it is still uncertain for other ones." (PMID 18086302, 2007). "(2025) demonstrated that tumor cells at the leading-edge area of iCCA exhibit enhanced proliferation and are closely associated with stromal components, including endothelial cells and POSTN+ FAP+ fibroblasts." (PMID 41394868, 2025). "In addition, the CRC patients with both periostin-positive and Smad2/3-positive CAFs were closely associated with venous invasion, tumor relapse, and a highly advanced stage." (PMID 39941916, 2025). "Pan-cancer analysis of TCGA database has provided evidence that individuals with high POSTN or FAP expression are associated with a high Tumor Immune Dysfunction and Exclusion (TIDE) score, indicating greater potential for immune evasion and unfavorable prognosis from immunotherapy." (PMID 39107856, 2024). "In addition, a high expression of POSTN (in tumor cells and CAFs) was associated with shorter survival among patients with NSCLC." (PMID 39272978, 2024). "In addition, a significant increase in POSTN expression in tumor cells was also associated with many metastases to regional lymph nodes in the overall NSCLC group (pN2; * p < 0.05)." (PMID 39272978, 2024). "POSTN is highly regulated in cancer-associated stromal cells, suggesting that signals from tumor cells, such as TGF-β, may primarily trigger POSTN expression in the cancer-associated ECM." (PMID 38504252, 2024). "Significantly fewer plasma cells and more Periostin- as well as SMA-positive tumor-associated fibroblasts could be detected in CK6-expressing tumor samples." (PMID 36971797, 2023). "Periostin has variant C-terminal splicing forms, so pharmacological inhibition of cancer-specific or CAF-specific variants of periostin may effectively suppress tumor expansion and overcome chemoresistance." (PMID 36672284, 2023). "The ratios of CD8+ T cells and CD4+ T cells in PanCK− stromal cells were negatively correlated with the existence of POSTN+ cells in the tumour regions (R = −.63, P = 3.5e−15; R = −.58, p < .0001), suggesting that POSTN+ CAFs were associated with lower infiltration of T cells in NSCLC." (PMID 38115703, 2023).
tumor (continued). "Moreover, its expression seems associated with aggressive tumor behavior, advanced stage, and poor prognosis in most human tumors, except for BUCs in which POSTN seems to be downregulated." (PMID 38076555, 2023). "The activation of Akt signaling pathways in macrophages, induced by the secretion of Periostin from eCAFs, could potentially serve as a causal factor leading to alterations in the tumor microenvironment." (PMID 37686288, 2023). "Furthermore, we demonstrated that POSTN expression or the abundance of POSTN+ CAFs were significantly associated with advanced tumour stages and poor prognosis in NSCLC." (PMID 38115703, 2023). "In addition, a matrix protein periostin (PN) has been found, which is secreted by cancer-associated fibroblasts in the tumor microenvironment and can promote tumor growth, proliferation, metastasis, and angiogenesis through various mechanisms." (PMID 37284316, 2023). "POSTN also has a multifaceted role in tumor-associated ECM remodeling." (PMID 37350937, 2023). "Finally, we investigated the presence of POSTN+ CAFs in different tumour stages, and their potential association with tumour progression and prognosis." (PMID 38115703, 2023). "Despite the loss of Periostin, tumor growth was promoted in the TAC-operated mice." (PMID 38139195, 2023). "As a gene with survivorship differences, POSTN can induce the accumulation of tumor-associated macrophages around the tumor cells and may play a supportive role for TAMs in tumor progression." (PMID 35832544, 2022). "Importantly, we showed that the combination of periostin‐positive CAFs and podoplanin‐positive CAFs was associated with specific tumor microenvironment features in terms of stromal abundance and immune cell infiltrates." (PMID 36102377, 2022). "Additionally, periostin is an inflammatory/immune factor that recruits and polarizes tumor-associated macrophages and activates T helper 2 (Th2) lymphocytes, both of which support cancer progression and chemoresistance." (PMID 35850759, 2022). "POSTN is a protein secreted by both tumor cells and cancer-associated fibroblasts (CAFs)." (PMID 36077762, 2022). "Considering the association observed between stromal periostin staining and tumor grade, we envisioned the possibility that circulating periostin may be a potential marker to identify high-grade PCa carriers." (PMID 35887333, 2022). "In addition, several molecules associated with tumor mechanisms and related to tumor immune responses such as gelsolin, periostin, osteopontin, lumican and vitamin D, were identified in the PC secretome dependent on GB-induced CMA." (PMID 35419364, 2022). "The most important of them are tumor-associated macrophages (TAMs), myeloid-derived suppressor cells (MDSCs) and cancer-associated fibroblasts (CAFs) CAFs are responsible for the production of periostin, which is the subject of our research." (PMID 35056404, 2022). "Importantly, high expression of FAP, CD29, or periostin in tumor tissues is associated significantly with poor overall survival of the patients." (PMID 32932015, 2021). "The periostin exerts an immunomodulatory effect on tumor-associated macrophages in cancer." (PMID 32688410, 2020). "Next, we examined whether fibronectin and periostin expression in tumor stroma, analyzed jointly, showed an association with overall survival." (PMID 31936272, 2020). "The expression of periostin in the desmoplastic stroma of the tumor has been associated with the aggressiveness of tumor behavior, increased metastatic potential, and advanced tumor stages in multiple cancer types, such as head and neck, colon, breast, lung, and others." (PMID 32719746, 2020). "This may be an underlying mechanism explaining why, in cancer, high periostin levels reflect aggressive tumor behavior, advanced stage, and poor prognosis." (PMID 32000779, 2020). "Furthermore, high POSTN protein expression was associated with aggressive molecular tumour features and shorter survival." (PMID 30575030, 2019).
tumor (continued). "Furthermore, it was reported that periostin, a disulfide-linked cell adhesion protein, plays an important role in tumor progression." (PMID 31450710, 2019). "In general, high POSTN levels are usually associated with a more aggressive tumor behavior, advanced stage or poor prognosis, suggesting that POSTN levels could be a useful prognostic biomarker." (PMID 29946533, 2018). "Moreover, periostin was shown to be a critical player in cancer progression and metastasis, by promoting the recruitment of tumor-associated macrophages in the cancer tissue or by interacting with and permitting the colonization of cancer cells." (PMID 28536691, 2017). "The link between ERRα/POSTN in the clinical models was confirmed by our meta-analyses of bone metastases and in tumor adjacent tissues in primary tumors, which suggests that POSTN may constitute a new prognostic marker in association with ERRα." (PMID 27776343, 2016). "Cancer cells can induce fibroblast-mediated accumulation of stromal POSTN and POSTN derived from cancer stem cells can recruit M2 tumor-associated macrophages and promotes malignant growth, indicating that POSTN bridges cancer cells and cancer-supportive stromal cells." (PMID 26556874, 2016). "Investigating the mechanism of POSTN-induced metastasis, Malanchi and colleagues reported a decrease in colony formation in vitro with POSTN-deficient tumor cells or wild-type CSCs co-cultured with POSTN-deficient stromal cells, demonstrating the involvement of POSTN in stem cell maintenance." (PMID 26086719, 2015). "In addition, several proteins such as enolase, vimentin, peroxiredoxin 5, Hsp 70, periostin precursor, RhoA, cathepsin D preproprotein, and annexin 1 were found to be associated with the tumor responses to treatment within each subtype." (PMID 22110952, 2011). "In some instances, periostin expression levels were higher than 3000 in the tumor but negligible in matching cell lines, suggesting that periostin expression may be very high in tumor-associated stromal cells." (PMID 18086302, 2007). "Recently, periostin (POSTN), a gene encoding a protein with similarity to the fasciclin family and involved in cell survival and angiogenesis, has emerged as a promising marker for tumor progression in various types of human cancers." (PMID 18086302, 2007). "The expression of Periostin in various types of cancers suggests that Periostin may be intimately associated with the progression of tumour development." (PMID 17060937, 2006). "Furthermore, the production of POSTN by cancer-associated stromal cells may be further reduced due to fewer maintenance signals from tumor cells." (PMID 38504252, 2024). "In addition, we were able to show that POSTN expression was predominantly localised in tumour stroma cells, i.e., in CAFs, as evidenced by the positive IHC staining and a very similar pattern in the serial sections for POSTN and CAF-associated markers, i.e., α-SMA, D2-40, and vimentin." (PMID 32987711, 2020). "The emergence of ECM signatures to stratify patients with cancer is already providing useful predictors of disease staging, and ECM molecules such as tenascins, periostin, and versicans have been linked to tumour progression and eventually could be used to identify early signs of metastasis." (PMID 30135716, 2018). "Periostin was originally called osteoblast specific factor-2 and in this study we have shown that periostin is highly expressed in reparative lesions associated with osteoid/woven bone formation, such as fracture callus and myositis ossificans as well as in benign and malignant bone-forming tumours." (PMID 30202513, 2018). "However, the detailed tumor-associated angiogenesis function of POSTN in PaC remain to be explored." (PMID 27223086, 2016). "POSTN+ CAFs have recently been reported to differentiate from HSCs, predominantly located in the peripheral tumor region and dominates ECM remodeling compared to other CAF subsets." (PMID 41018265, 2025).
tumor (continued). "POSTN is expressed in diverse tissues and is involved in various processes including hyperplasia, fibrosis, and tumor metastasis." (PMID 41567981, 2025). "Periostin (POSTN), secreted by CAFs, accelerates angiogenesis, tumor invasion, and EMT via integrin interaction." (PMID 40766310, 2025). "Threshold effect analysis was used to identify the optimal threshold for POSTN expression, and an in vitro experiment was conducted to evaluate the effect of POSTN on tumor cell growth and invasion." (PMID 40991535, 2025). "The role of periostin (POSTN) in regulating the immunosuppressive environment in tumor metastasis sites was seldom documented." (PMID 39947253, 2025). "Together, SPP1+ macrophages and POSTN+ CAFs form physical and biochemical tumor immune barriers (TIBs) that shield tumor cores from T-cell access and reduce the efficacy of immune checkpoint blockade (ICB) therapies." (PMID 40507341, 2025). "Immunoprecipitation, immunofluorescence and co-culture system were used to clarify the mechanism of POSTN-NOTCH1 axis in tumor cells-hepatic stellate cells (HSCs) crosstalk." (PMID 39762921, 2025). "Subcutaneous xenograft model and liver metastasis model were established to examine the anti-tumor growth and metastases effect of targeting POSTN-NOTCH1 signaling axis." (PMID 39762921, 2025). "At the advanced stages of tumor progression, periostin promotes the metastatic development of tumors by binding to αvβ3 integrins, thereby activating the Akt/PKB cell survival signaling pathway." (PMID 39941916, 2025). "Theses 13 genes (e.g., COL1A1, POSTN, ASPN, PDGFRA, MUC4, SPARC), implicated notably in EMT and cancer progression, were found to be highly expressed in depth of tumor ID15 and ID08, near the invasive margin." (PMID 40076457, 2025). "In our PUCH-PDAC cohort, we validated a significant correlation between CAF-derived POSTN expression and tumor malignancy, as well as worse clinical prognosis." (PMID 40520021, 2025). "Our study reveals that SCLC-derived POSTN mediates collagen deposition and liver fibrosis, highlighting its crucial role in shaping the tumor microenvironment." (PMID 39762921, 2025). "POSTN (periostin) plays a pivotal role in tumour progression by interacting with ECM components and engaging WNT and NOTCH1 signalling pathways." (PMID 40038875, 2025). "Additional ARGs, including PDGFA, VTN, and POSTN, revealed intricate and subtype-specific correlations with both macrophages and T cells, reinforcing their involvement in shaping the tumor immune landscape." (PMID 40943183, 2025). "Elevated POSTN expression was observed with advancing tumor stage, poor differentiation, and greater tumor size, and was significantly associated with vascular invasion, lymph node metastasis, and distant metastasis." (PMID 40520021, 2025). "Both the periostin-positive tumor stroma group and the Smad2/3-positive cancer cells group showed significant correlations with venous invasion (p = 0.023), a high relapse rate (p = 0.014), and a high advanced stage (p = 0.035)." (PMID 39941916, 2025). "Periostin has been reported to be synthesized by either cancer cells or surrounding tumor stromal cells, such as CAFs, within the tumor microenvironment." (PMID 39941916, 2025). "POSTN interacts with integrin receptors, particularly αvβ3 and αvβ5, establishing a critical signaling nexus that enhances tumor cell behavior in HCC progression." (PMID 41018265, 2025). "Although fibroblast-mediated remodeling or secretion of ECM components within metastatic sites is known to promote circulating tumor cell seeding and outgrowth, the specific upregulation of periostin by LFs in response to OS EVs is intriguing." (PMID 40099972, 2025). "POSTN secreted by tumor cells mainly directly binds to integrins, activates the MAPK/ERK and AKT/mTOR signaling pathways, and thereby promotes metastasis and proliferation." (PMID 41018265, 2025).
tumor (continued). "Mechanistically, POSTN interacts with integrin ITGAV/ITGB5 on tumor cells, activating the PI3K/AKT/β-catenin pathway and promoting epithelial-mesenchymal transition (EMT) phenotype." (PMID 40520021, 2025). "POSTN encodes periostin, a secreted ECM protein implicated in tumor progression, extracellular remodeling, and EMT." (PMID 41093273, 2025). "Crucially, POSTN sustains the stem-like properties of tumor cells, contributing to chemoresistance by enhancing their survival mechanisms and transcriptional plasticity, enabling the evasion of therapeutic interventions." (PMID 40520021, 2025). "The intensity of POSTN protein expression in SEMs was weak in 37 tumours (60.70%), moderate in 13 (21.30%) and high in 6 case (9.80%)." (PMID 41361308, 2025). "Ovarian tumor stroma exemplifies these dynamics: TGF-β1–induced periostin in activated fibroblasts promotes desmoplastic remodeling and malignant cell motility, reinforcing matrix-rich interfaces at tumor borders that are unfavorable to T-cell ingress." (PMID 41181126, 2025). "Based on our IHC scoring standard, POSTN protein expression increased markedly in tumor tissues compared with that in adjacent normal tissues (P < 0.001), consistent with the scRNA-seq results." (PMID 40520021, 2025). "We examine the current state of ECM research, focusing on key components such as collagen, laminin, fibronectin, periostin, and hyaluronic acid, and their roles in tumor biology." (PMID 40426238, 2025). "This study found that the intracellular level of POSTN directly regulates the proliferation and invasion of tumor cells, exhibiting a cell-autonomous effect." (PMID 40991535, 2025). "Substantiating this premise, EC4 subclass analysis identified conserved functional modules including ECM remodeling effectors (HSPG2,MGP,POSTN) and tumor niche-modifying factors (RAMP2,ACKR1,CD74)." (PMID 41394809, 2025). "POSTN (periostin), a matricellular protein involved in cell‐matrix interactions, is often overexpressed in cancers, promoting tumour growth, invasion and metastasis." (PMID 40038875, 2025). "We have shown that the tumour-promoting and chemoprotective properties of CAFs are associated with an activated myofibroblast (α-Smooth Muscle Actin/ACTA2+, Periostin/POSTN+) phenotype that can be reversed with phosphodiesterase type 5 inhibitors (PDE5i)." (PMID 40640495, 2025). "In summary, short-term effects of ADT were observed on tumor cell nuclear AR levels and apoptosis, as well as on stromal POSTN and PDGFRB levels." (PMID 40841830, 2025). "The expressions of periostin and Smad2/3 in the tumor specimens were examined by immunohistochemistry." (PMID 39941916, 2025). "POSTN is a secretory extracellular matrix protein predominantly expressed by fibroblasts within the tumor stroma of PDAC tissues." (PMID 40520021, 2025). "POSTN also stimulates the expression of TGF-β2, which activates normal fibroblasts into cancer-associated fibroblasts (CAFs), further supporting tumor growth and invasion." (PMID 40330466, 2025). "Elevated expression of POSTN in SCLC is correlated with accelerated tumor progression and metastasis." (PMID 39762921, 2025). "Key upregulated proteins included LGALS3 (Galectin 3), an established marker of thyroid malignancy 22, and POSTN (Periostin), which promotes tumor metastasis and angiogenesis." (PMID 40861812, 2025). "While MMP-9, TNC, and POSTN support tumor progression through ECM remodeling, CD163 is involved in tumoral immune suppression." (PMID 41450913, 2025). "POSTN participates in tumor-proximal intravasation processes by elevating epithelial-mesenchymal transition (EMT) and motility of clear cell renal cell carcinoma." (PMID 39762921, 2025). "In contrast, metastases with type 2 stroma contained less bone and had more ERG + blood vessels and POSTN + cells, exhibiting higher tumor proliferation and lower PSA levels." (PMID 40841830, 2025).